EPO (erythropoietin)
Diseases named in the same sentence as EPO in open-access papers (continued):
Sharing a sentence is not in itself a finding about the gene and the disease.
Glucose intolerance (7 papers, 2009 to 2025). Glucose intolerance (GI) can be defined as dysglycemia that comprises both prediabetes and diabetes. "In the present study, we fed C57BL/6 mice with HFD to establish glucose intolerance and investigated the effects of EPO treatment on glucose tolerance and the potential molecular mechanisms underlying the action of EPO in regulating gluconeogenesis and inflammation in the liver." (PMID 23326455, 2013). "In the present study, we found that EPO treatment significantly reduced the body weights and improved glucose intolerance in the HFD-fed mice." (PMID 23326455, 2013). "Our data indicated that EPO treatment significantly reduced the body weights and the levels of fasting blood glucose and serum insulin, and improved glucose intolerance in the HFD-fed mice." (PMID 23326455, 2013). "This weight reduction is followed by a normalisation of several metabolic parameters including diet-induced glucose intolerance in the high-fat fed EPO transfected mice." (PMID 19521513, 2009). "Despite a 28-fold increase in plasma EPO, anemic mice showed elevated glycemia and glucose intolerance, which ruled out glucose lowering action of EPO while corroborating a strong inverse association of blood glucose with the concurrent hematocrit." (PMID 40238885, 2025). "Collectively, our data suggest that EPO may activate the Akt pathway and inhibit gluconeogensis and inflammation-related signaling in the liver, leading to the improvement of glucose intolerance in the HFD-fed mice." (PMID 23326455, 2013). "Therefore, our data indicated that EPO treatment improved glucose intolerance by inhibiting gluconeogenesis and inflammation in the livers of HFD-fed mice." (PMID 23326455, 2013). "We found that EPO treatment significantly reduced the body weights in HFD-fed mice and we speculate that EPO treatment may also enhance fat oxidation in the liver, contributing to the improvement of glucose intolerance in the HFD-fed mice." (PMID 23326455, 2013). "Therefore, our novel findings may provide new insights into the regulation of EPO on inflammation-related glucose intolerance." (PMID 23326455, 2013). "EPO treatment significantly reduced the body weights and the levels of fasting blood glucose and serum insulin and improved the HFD-induced glucose intolerance in mice." (PMID 23326455, 2013). "The glucose intolerance observed in male and female mice lacking estrogen receptor α was improved by EPO treatment, independent of changes in body weight and fat mass." (PMID 39996752, 2025).
hemorrhage (7 papers, 2012 to 2025). Loss of blood from the vascular compartment to the exterior or into nonvascular body space as a result of rupture or severance of the blood vessels. "Following hemorrhage or erythropoietin (EPO) administration, ERFE inhibits hepcidin expression in the hepatocytes." (PMID 41515226, 2025). "To shed light on this issue, we investigated erythropoietin (Epo), erythropoietin receptor (EpoR), and Y-box binding protein 1 (YB-1) concentrations in the fracture zone in a porcine MT + traumatic hemorrhage (TH) model." (PMID 36639666, 2023). "In a preclinical ICH study, ICH + EPO showed better functional recovery with a lower hemorrhage volume." (PMID 34685473, 2021). "Expanded erythropoiesis, as after hemorrhage or erythropoietin treatment, blocks hepcidin through an acute reduction of transferrin saturation and the release of the erythroblast hormone and hepcidin inhibitor erythroferrone." (PMID 31649559, 2019).
hip fracture (7 papers, 2012 to 2024). Traumatic or pathological injury to the hip in which the continuity of either the femoral head, femoral neck, intertrochanteric or subtrochanteric regions is broken. "For this reason, blood management using iron supplements and/or EPO and/or anti-fibrinolytics should be considered when planning the treatment strategy for hip fracture patients with several risk factors for ABT." (PMID 32871921, 2020). "Although incidence of hip fractures decreased among the general population in the United States after 1990, hip fracture incidence increased among hemodialysis patients coincident with EPO use and dose escalation up to 2004." (PMID 34603036, 2021). "Additionally, an analysis of the United States Renal Data System dataset revealed a proportional variation in hip fracture incidence with the annual sum of EPO doses in patients undergoing hemodialysis." (PMID 39835325, 2024). "We think that this trial will contribute to the knowledge about the safety and efficacy of ferric carboxymaltose with/without erythropoietin in preventing red-cell pack transfusions in patients with hip fracture." (PMID 22353604, 2012). "In conclusion we think that this trial will contribute with evidence about the safety and efficacy of ferric carboxymaltose with or without EPO in preventing RPC transfusions in patients with hip fracture." (PMID 22353604, 2012).
hypercoagulability (7 papers, 2007 to 2025). "Additionally, anabolic steroids, methotrexate, erythropoietin, corticosteroids, chemotherapeutic agents, and cyclooxygenase 2 inhibitors have also been associated with elevated hypercoagulability." (PMID 34011408, 2021). "EPO can increase PLT and RBCs count and blood viscosity, which can both cause hypercoagulability and increase the risk of thrombosis." (PMID 36539891, 2022). "These may contribute to hypercoagulability through erythropoietin-driven marrow activity and reactive thrombocytosis." (PMID 40565811, 2025).
hyperthyroidism (7 papers, 2013 to 2025). Overactivity of the thyroid gland resulting in overproduction of thyroid hormone and increased metabolic rate. "Interestingly, hyperthyroidism is associated with increased total number of red blood cells, likely due to increased tissue oxygen demands resulting in increased erythropoietin secretion." (PMID 24319463, 2013). "Despite elevated erythropoietin, haemoglobin levels are usually normal or even decreased in hyperthyroidism, possibly due to altered iron metabolism, haemolysis and oxidative stress leading to shortened erythrocyte survival." (PMID 39356807, 2024). "This may result from the increased action of hepcidin and erythropoietin coupled with the decreased action of thyroid-stimulating hormone (TSH) in hyperthyroidism." (PMID 39518858, 2024). "Normalization of hemoglobin levels following treatment of hyperthyroidism was accompanied by increases in mean corpuscular volume (MCV) and total iron-binding capacity (TIBC), while ferritin and erythropoietin (EPO) levels decreased." (PMID 26866603, 2016). "Those authors suggested that erythrocytosis in hyperthyroidism may result from the activation of HIF-1α, leading to increased expression of the EPO gene." (PMID 39518858, 2024). "Thus, it seems possible that similar mechanisms (T3 → TRβ/RXRα → HLF → HIF-1α → EPO and T3 → SHH → BMP-4 → BFU-E) may lead to increased erythropoiesis in human and feline hyperthyroidism and may explain the presence of erythrocytosis observed in this disease." (PMID 39518858, 2024).
liver cancer (7 papers, 2020 to 2025). An epithelial or non-epithelial malignant neoplasm that arises from the liver. "In their rat model of liver cancer cachexia, EPO-associated increases in cardiac weight, stroke volume (SV), FS, and physical activity were hypothesized to be attributed to observed decreased levels of Trypsin." (PMID 35326491, 2022). "The expression levels of MYBL2, SPP1, CTSV and EPO were remarkably increased in liver cancer cells compared with normal liver cells, while the expression level of CYP2C9 was significantly decreased (p < 0.05)." (PMID 36650832, 2023). "In 1992, Dr. Semenza and Dr. Wang at Johns Hopkins University discovered a molecule that is necessary for the transcriptional activation of the erythropoietin (EPO) gene under hypoxic conditions in a liver cancer cell line (Hep3B), and named it HIF-1." (PMID 34884197, 2021). "Lastly, some liver cancer studies have identified pathological erythrocytosis and/or hepatic vascular lesions, potentially with EPO production and peliosis." (PMID 33084574, 2020). "In early in vitro experiments, IL-1 and TNF-α were found to inhibit erythropoietin expression in isolated rat kidney and human liver cancer cells, but it has not been confirmed in humans whether inflammatory factors inhibit EPO production." (PMID 32850902, 2020). "Differ from STC2 and BIRC5 which were mainly expressed in liver cancer cells, EPO and GLP1R did not exhibit specific expression in a certain cell type, which could potentially be attributed to the fact that EPO and GLP1R may not predominantly expressed in HCC cell lines." (PMID 40458412, 2025).
memory impairment (7 papers, 2017 to 2022). "A recent study in 6-day-old rat pups showed that a single dose of erythropoietin at the onset of hyperoxia (24 h 80% oxygen) improved memory impairment and reduced acute oligodendrocyte degeneration up to the adolescent and adult stage." (PMID 31850291, 2019). "Therefore, EPO showed a promising effect against learning and memory impairments induced by BRI 24 h after reperfusion." (PMID 29881418, 2018). "In sleep-deprived mice, amyloid-β (Aβ)-injected aging mice, and kainic acid-induced brain damage mice, TSG restored memory impairment through the induced expressions of erythropoietin, PPAR-γ coactivator 1α (PGC-1α), and hemoglobin in astroglia and neurons of the hippocampus." (PMID 29801454, 2018).
mood disorder (7 papers, 2018 to 2025). A cognitive disorder a disturbance in which the person's mood is hypothesized to be the main underlying feature. "We first examine published associations between EPO administration, mood disorders, cognition and hippocampal volume." (PMID 30310078, 2018). "If this trial reveals pro-cognitive effects of EPO, this may influence future treatment of mood disorders and/or preventive strategies in at-risk populations." (PMID 30400939, 2018). "A recent study involving EPO-treated patients with mood disorders showed that the neural basis for their cognitive improvements appeared to involve an increase in hippocampal volume." (PMID 30310078, 2018). "In our double-blinded randomized trials of the effects of 8 weeks of EPO treatment, we included 84 patients with mood disorders over a 3-year period (2009–2012)." (PMID 29673379, 2018). "Here we have reviewed literature that examines the relationship between EPO, mood disorders, cognition and the hippocampus." (PMID 30310078, 2018). "Future studies investigating the effects of EPO on different cellular networks mediated by GSK3β are highly warranted to identify its common and specific roles in the treatment of mood disorders and other neuropsychiatric illnesses." (PMID 30310078, 2018). "Because of the lack of effective treatments targeting cognitive dysfunction in mood disorders, the use of a placebo group is necessary for investigating potential beneficial cognitive effects of EPO." (PMID 30400939, 2018). "Taken together, preliminary findings highlight EPO as a candidate treatment for ECT-induced cognitive deficits in mood disorders." (PMID 29673379, 2018). "We conclude by suggesting how this developing area of research can be further advanced, such as using pharmacogenetic studies of EPO treatment in patients with mood disorders." (PMID 30310078, 2018). "Erythropoietin (EPO) is a promising treatment for cognitive dysfunction in mood disorders and for counteracting ECT-induced cognitive side effects." (PMID 29673379, 2018). "Further work that explores molecular mechanisms related to the inhibition of GSK3β function and the promotion of EPO function within a mood disorder and cognition framework is highly warranted." (PMID 30310078, 2018). "We have previously conducted a double-blinded randomized trial of eight weeks of EPO treatment in 84 patients with mood disorders at the Psychiatric Centre Copenhagen, Rigshospitalet." (PMID 30400939, 2018). "The aim of this review is to describe the potential importance of glycogen synthase kinase 3-beta (GSK3β) as a multi-potent molecular mechanism of EPO-induced hippocampal volume change in mood disorder patients." (PMID 30310078, 2018). "Moreover, EPO has also great potential for the treatment of stress-related neurological disorders, including mood disorders." (PMID 34987412, 2021). "Unearthing the cellular pathways governed by EPO may enhance translation of targeted therapeutic strategies for mood disorders and other related conditions." (PMID 30310078, 2018). "However, the biological mechanisms linking EPO to increased hippocampal volume in mood disorders remain unknown." (PMID 30310078, 2018). "We observed no serious adverse events of 8 weekly EPO infusions in the proposed dose and administration form in our previous studies including patients with mood disorders." (PMID 29673379, 2018). "Additional research is required to elucidate the role of the EPO gene (OMIM: 133170) and its related genetic variation; surprisingly, this has not been studied in mood disorders (or psychiatric disorders more generally)." (PMID 30310078, 2018).
myelofibrosis (7 papers, 2016 to 2025). A partial or complete replacement of the bone marrow stroma by fibrous tissue. "This uremic toxin inhibits erythropoietin by causing myelofibrosis." (PMID 39791168, 2025). "Erythrocyte lifespans decrease in response to high PTH levels; and high PTH levels inhibit hematopoietic stem cell activity, particularly that of erythroid burst-forming units, as well as inducing myelofibrosis and contributing to erythropoietin resistance." (PMID 27764168, 2016). "The patient was considered immunocompromised due to underlying myelofibrosis with disease-related cytopenias, particularly anemia and relative lymphopenia, which are recognized risk factors for opportunistic infection; erythropoietin therapy itself is not immunosuppressive." (PMID 41141097, 2025). "We describe a case of a 15-year-old boy with myelofibrosis due to secondary HPT who was successfully treated with hemodialysis, erythropoietin, phosphate binders, and activated vitamin D agents." (PMID 34046371, 2021).
neonatal encephalopathy (7 papers, 2021 to 2025). "We have seen similar LPS-induced increases in EPO in infants with neonatal encephalopathy in the first days of life consistently." (PMID 40661891, 2025). "Additionally, recombinant erythropoietin (rEPO) has been shown to improve both histological and functional outcomes in studies involving neonatal encephalopathy." (PMID 39554309, 2024). "We examined whether erythropoietin monotherapy improves neurodevelopmental outcomes in near-term and term infants with neonatal encephalopathy (NE) in low-middle income countries (LMICs)." (PMID 34175900, 2021). "Despite there have been several studies neuroprotective therapy for neonatal encephalopathy, such as the use of erythropoietin, Xenon, antioxidants and some neuroprotective medicine, none of them was proved to be effective on NE due to the lack of solid evidence-based reports." (PMID 34972144, 2021).
nephrotic syndrome (7 papers, 2012 to 2025). A collection of symptoms that include severe edema, proteinuria, and hypoalbuminemia; it is indicative of renal dysfunction. "Studies in both humans and animals have reported substantial urinary losses of EPO in nephrotic syndrome." (PMID 40620843, 2025). "Excessive urinary losses of iron, TF, EPO, transcobalamin, and some metals were found in patients with nephrotic syndrome." (PMID 36855344, 2023). "Proposed mechanisms for erythrocytosis in patients with renal tubular acidosis and nephrotic syndrome include increased erythropoietin secretion due to intra renal hypoxia and increased secretion of interleukin 8 which in turn stimulate erythropoiesis." (PMID 22834973, 2012). "Increased erythropoietin levels due to intrarenal hypoxia and IL 8 mediated bone marrow stimulation are the proposed mechanisms of erythrocytosis in patients with nephrotic syndrome." (PMID 22834973, 2012). "Proposed mechanisms of polycythaemia in patients with nephrotic syndrome and distal renal tubular acidosis include, increased erythropoietin production and secretion of interleukin 8 which in turn stimulate erythropoiesis." (PMID 22834973, 2012).
Pancytopenia (7 papers, 2021 to 2025). An abnormal reduction in numbers of all blood cell types (red blood cells, white blood cells, and platelets). "It has been previously shown that G-CSF, granulocyte-monocyte colony-stimulating factor (GMCSF), pegylated G-CSF (pegfilgrastim), interleukin-11, interleukin-3, and erythropoietin have regenerative effects on pancytopenia." (PMID 40429945, 2025). "Additional laboratory testing showed pancytopenia with low erythropoietin as well as low thyroid hormone levels." (PMID 33807868, 2021). "Hemodialysis and erythropoietin were initiated and combined therapy with a phosphate binder and an active vitamin D agent achieved greater reduction of PTH levels, along with improvement of pancytopenia." (PMID 34046371, 2021).
pneumonia (7 papers, 2011 to 2025). An acute, acute and chronic, or chronic inflammation focally or diffusely affecting the lung parenchyma, caused by an infection in one or both of the lungs (by bacteria, viruses, fungi, or mycoplasma.). "Furthermore, pneumonia was associated with age, cardiovascular diseases, serum phosphorus levels, and a need for higher erythropoietin dosages." (PMID 34268290, 2021). "Immunosuppressant administration for 16 days did not increase the occurrence of AEs in groups A and B. In the previous trial, pneumonia and irritability occurred more in the UCB- and the EPO-administered groups, possibly because of the long 1-month duration of immunosuppression treatment." (PMID 33246489, 2020).
polycystic kidney (7 papers, 2014 to 2024). "Our findings suggest that the mechanisms governing erythropoietin production in native polycystic kidneys continue to function following renal transplantation." (PMID 38427307, 2024). "The lower ERI in polycystic kidney disease patients is expected as it is thought that interstitial cells adjacent to the walls of the proximal-type cysts can produce erythropoietin, resulting in higher Hb concentrations and therefore lower ESA requirements." (PMID 29178879, 2017). "We have expected the dose of ESA to be lower in ADPKD, as synthesis of erythropoietin in polycystic kidneys is maintained even at late stages of the disease." (PMID 26282281, 2015). "The EPO level was 372 mU/ml (normal range, 8–36 mU/ml), and CT exhibited a considerably enhanced lesion in the left polycystic kidney." (PMID 25295086, 2014).
pulmonary embolism (7 papers, 2011 to 2024). The obstruction of the pulmonary artery or one of its branches by an embolus, sometimes associated with infarction of the lung. "As a thromboembolic event, one pulmonary embolism was observed in the EPO group." (PMID 21959870, 2011). "In the current study, one pulmonary embolism was observed during treatment with EPO, but no death due to thromboembolic events was reported." (PMID 21959870, 2011). "Another two studies demonstrated that EPO did not increase the incidence of pulmonary embolism." (PMID 36582613, 2022).
Reticulocytopenia (7 papers, 2013 to 2025). A reduced number of reticulocytes in the peripheral blood. "SMA is often associated to reticulocytopenia, erythroid hyperplasia and increased levels of erythropoietin (EPO), suggesting a functional disruption of RBCs precursors." (PMID 23358441, 2013). "Erythropoietin should also be considered in case of reticulocytopenia." (PMID 40439782, 2025). "The addition of erythropoiesis-stimulating agents (ESA) such as recombinant erythropoietin (rEPO), may be beneficial based on retrospective data, especially when there is (relative) reticulocytopenia." (PMID 37795092, 2023). "Importantly, inadequate endogenous EPO levels have been demonstrated in most AIHA cases with reticulocytopenia, and the administration of recombinant EPO induced a response in up to 70% of them." (PMID 33261016, 2020).